BDNF (brain derived neurotrophic factor)
Diseases named in the same sentence as BDNF in open-access papers (continued):
Sharing a sentence is not in itself a finding about the gene and the disease.
tumor (continued). "It has been reported that BDNF is a secretory protein, produced by tumor cells to promote their growth and survival." (PMID 26926340, 2016). "The score of immunostaining intensity, evaluated by Image J in the different tumor samples was also indicated for each labelled protein as well as double-positive expression for p75NTR and pro-BDNF." (PMID 27120782, 2016). "Subsequent analyses of immunohistochemically labelled NGF, BDNF, TrkA, and TrkB proteins in a set of seven tumor samples from seven patients with ES revealed heterogenous expression of these proteins across tumor samples." (PMID 27145455, 2016). "Whereas pro-BDNF/BDNF, TrkB and sortilin were expressed in normal tissues, mainly in tubules, their expressions were also detected in tumor areas." (PMID 27120782, 2016). "The overexpression of BDNF was found in 20 tumor samples in comparison with the non-tumor counterparts (p = 0.000)." (PMID 26926340, 2016). "Several studies point out the involvement of BDNF in tumor pathogenesis through TrkB in different cancers such as colon, lung, breast neuroblastoma, ovary prostate, head and neck, as well as lymphoid malignant B cells and myeloma." (PMID 27120782, 2016). "BDNF is a secretory cytokine, which is prepared by tumor cells and promotes growth and survival of themselves." (PMID 26926340, 2016). "TRKB, which is important for neural development and is an independent prognostic marker in many tumor types, is the receptor of brain-derived neurotrophic factor (BDNF)." (PMID 27438705, 2016). "We demonstrate that the intracerebral administration of BDNF induces reduction of tumour size and inhibition of M/Mφ infiltration and activation (as CD68 staining)." (PMID 25818172, 2015). "This environment–brain–tumour connection appears to be mediated by IL-15 and BDNF, cytokines whose level increases in the brain of EE-housed mice." (PMID 25818172, 2015). "K252a followed by BDNF treatment inhibited the anoikis resistance of tumor cells, as compared with BDNF treatment." (PMID 24801982, 2014). "BDNF increased tumor cell viability, migration, invasion and inhibited anoikis in the TrkB-expressing CRC cell lines." (PMID 24801982, 2014). "To explore the possibility of an autocrine BDNF/TrkB signaling loop occurring in CRC, we investigated the effect of BDNF on tumor cell viability in TrkB-expressing CRC cells." (PMID 24801982, 2014). "In patients with both primary tumor (A, C) and peritoneal metastatic nodules (B, D), human CRC cells at the peritoneal metastatic nodules expressed both BDNF and TrkB, as did those at the primary tumor." (PMID 24801982, 2014). "BDNF produced by platelets and/or endothelial cells would be able to stimulate the migratory capacity and survival of the detached tumor cells." (PMID 24959744, 2014). "Recent studies also demonstrated the molecular mechanisms of BDNF/TrkB signaling in tumor cell migration, invasion, and anoikis resistance." (PMID 24801982, 2014). "These lines of evidence indicated that BDNF/TrkB signaling promotes tumor progression, leading to a poor prognosis for various human malignancies, and that it has emerged as a potential therapeutic target." (PMID 24801982, 2014). "The mRNA levels of BDNF, TrkB and their co-expression in CRC tissues were associated with tumor progression and poor prognosis of CRC patients." (PMID 24801982, 2014). "In this public data set, univariate analyses showed that reduced BDNF expression is significantly associated with a shorter RFS, in particular in clinical important groups of patients with advcanced tumor stages." (PMID 25036590, 2014). "With regard to the BDNF/TrkB signaling in CRC, BDNF or TrkB was overexpressed in both clinical tumor samples and associated with aggressive tumor phenotypes." (PMID 24801982, 2014). "BDNF is expressed by several human tumors, and is a key regulator of oncogenesis, tumor invasion, and tumor progression." (PMID 23531103, 2013).
tumor (continued). "Activation of the BDNF/TrkB pathway stimulates tumor cell proliferation, angiogenesis, and invasion and metastasis and causes chemotherapy resistance." (PMID 23936232, 2013). "As previously reported, screening of clinical samples has revealed that BDNF is highly expressed in colon carcinoma compared with non-tumor tissues." (PMID 24255678, 2013). "BDNF expression directly enhances the proliferation, survival, migratory capability, and invasiveness of tumor cells." (PMID 23531103, 2013). "Here, we have demonstrated roles of the BDNF/TrkB signaling system in choriocarcinoma cell invasion and metastasis, in addition to its roles in tumor growth at primary site." (PMID 24403258, 2013). "Immunohistochemical staining showed only a small increase in BDNF protein in tumor tissues, compared with that in normal background colorectal tissues." (PMID 24255678, 2013). "Activation by BDNF promoted significant upregulation of tumor cell growth and motility of both Ishikawa and RL95-2 cell lines." (PMID 23936232, 2013). "Our previous study has shown that the BDNF-TrkB signaling axis contributes to tumor invasion and progression of HNSCC in xenograft animal models." (PMID 22276165, 2012). "Although it is clearly evident that TrkB/BDNF system plays a role in tumor progression and metastasis, the molecular mechanisms underlying BDNF-induced chemoresistance development are not fully understood." (PMID 22276165, 2012). "Antisense inhibition of BDNF activity in ARH cells also decreased tumor burden and prolonged survival in SCID-rab mice." (PMID 23077504, 2012). "Taken together, our study confirmed that both BDNF and TrkB were higher expressed in multiple HCCs, which was positively correlated with tumor progression." (PMID 21999199, 2011). "BDNF emerged as a growth factor significantly up regulated amongst ER-α positive tumours in both the screening and validation sets." (PMID 21767406, 2011). "BDNF and its high-affinity receptor TrkB are well studied to facilitate apoptosis resistance and metastatic tumor cells survival." (PMID 21999199, 2011). "BDNF, TrkB145, and TrkB95 expression was higher in tumors than in non-tumor tissues from the same patient and in control (megadolichocolon) tissues." (PMID 21966426, 2011). "In PDAC, tumor‐derived BDNF promotes axonogenesis and increases nerve density in the tumor mass." (PMID 41556039, 2026). "Moreover, no prior research has explored the potential mediating role of gut microbiota profiles, inflammatory biomarkers (e.g., CRP, fecal calprotectin), and microbial metabolites (e.g., TMAO, BDNF) in linking diet to psychological and tumor‐related outcomes." (PMID 41142011, 2025). "Importantly, several interventions (pharmacological, naturally derived, and traditional formulations) reduced neuroinflammation, normalized BDNF levels, and improved cognitive performance, both in tumor-bearing and healthy chemotherapy-treated animals." (PMID 41155372, 2025). "Therefore, targeting neurotrophic signals such as NGF, BDNF, and their respective receptors offers a promising strategy to disrupt tumor adaptive responses." (PMID 41163091, 2025). "This binding triggers the tumor cells to release brain-derived neurotrophic factor (BDNF), which enhances cancer innervation via activation of host neurotrophic receptor tyrosine kinase B receptors (NTRK2), thereby establishing a feed-forward loop of sustained signaling." (PMID 40359002, 2025). "This phenomenon may reflect an adaptive response of the organism to tumor-induced damage and inflammation, or the prolonged activation of microglial cells, which can trigger BDNF release." (PMID 41155372, 2025). "Second, alterations in BDNF levels can be impacted by numerous confounding variables, such as psychological disorders, tumor grade, age, gender, analgesic usage, and other bodily secretions, which could not be further addressed in this study." (PMID 39789839, 2025).
tumor (continued). "Recently, advances in cancer neuroscience have highlighted neurotrophins—nerve growth factor (NGF) and brain−derived neurotrophic factor (BDNF)—and their Trk/p75NTR receptors as modulators of tumor behavior and immune tone, offering a new strategy to recondition the osteosarcoma microenvironment." (PMID 41383615, 2025). "Notably, NGF and BDNF are upregulated across multiple cancers, including OS, where they correlate with enhanced tumour innervation, disease progression, and poor outcome." (PMID 41029717, 2025). "Finally, similar to MSC, we found that other components of the OS microenvironment ˗ specifically normal human osteoblasts or tumour-infiltrating monocytes ˗ can also promote axonal outgrowth, through mechanisms involving BDNF and IL-6." (PMID 41029717, 2025). "The BDNF signaling pathway’s presence in OPCs may be pivotal for neuronal-like functions within the tumor milieu." (PMID 39838429, 2025). "Moreover, BDNF supports angiogenesis, further embedding neural and vascular components within the tumor to sustain its growth." (PMID 41009819, 2025). "BDNF is a growth factor that can alleviate tumor cell death and promote angiogenesis." (PMID 40149331, 2025). "However, a significant increase in BDNF levels was observed both in tumor-bearing animals and in ovariectomized models." (PMID 41155372, 2025). "In this context, SUN2 acts as a tumor suppressor by downregulating the expression of brain‐derived neurotrophic factor (BDNF), thus inhibiting the BDNF/tropomyosin‐related kinase B signaling whose overexpression seemed involved in several carcinogenic processes." (PMID 39866838, 2025). "The data suggest that F3.CD-TK cells might have benefited the cervical neurocircuitry through neuroprotective and neurotrophic support (e.g., BDNF) in addition to reducing the tumor burden." (PMID 39329707, 2024). "We chose BDNF and cAMP as candidate treatments because previous studies have shown that neurotrophic factors are neuroprotective in RGCs across various models, and we sought to avoid treatments that directly interact with tumor suppressors or oncogenes." (PMID 38194296, 2024). "Studies have found that BDNF may affect patient prognosis by interacting with tumor-infiltrating Th2 cells, and thus may serve as a potential prognostic biomarker for PAAD." (PMID 38463521, 2024). "However, intravenous injection of BDNF (160 μg/kg) to TNFR2 knockout mice for 4 weeks increased tumor growth and SCZ-like behaviors as well as TrkB expression." (PMID 38592583, 2024). "Thus, even though the role of miR-30a:BDNF was not evaluated in the context of GB progression, it is possible that it has an important function in promoting tumor growth, as BDNF is known to induce cell survival." (PMID 38473710, 2024). "Endoplasmic reticulum stress in tumor cells may trigger the expression and release of BDNF into the TME." (PMID 38233872, 2024). "In salivary ACC, SCs have been shown to promote PNI by inducing the epithelial-to-mesenchymal transition (EMT) and the Schwann-like differentiation of tumor cells through the brain-derived neurotrophic factor (BDNF)–neurotrophic receptor tyrosine kinase 2 (NTRK2/TrkB) pathway." (PMID 38334648, 2024). "Observations distilled from this model tipped the scales towards a tangible diminution in tumor volume in subjects from both the miR134-mimics and miR134-mimics plus BDNF-NC groups vis-a-vis the NC group, the latter receiving an upswing in tumor volume post-treatment." (PMID 38579169, 2024). "TNF-α also increases the expression of brain-derived neurotrophic factor (BDNF) and tropomyosin receptor kinase B (TrkB) in the development of SCZ and tumor, but the role of TNFR in mediating the association between the two diseases remains unclear." (PMID 38592583, 2024). "Additionally, neuronal activity can affect the behavior of tumor cells by releasing proteins such as brain‐derived neurotrophic factor (BDNF), NLGN3, and insulin‐like growth factor‐1 (IGF‐1) in the microenvironment." (PMID 39469896, 2024).
tumor (continued). "Except for stimulation of neurogenesis, BDNF can induce tumor and endothelial cell migration." (PMID 38233872, 2024). "In addition to its role in cell proliferation and survival, BDNF/TRKB signaling has been associated with the epithelial–mesenchymal transition (EMT), a process involved in tumor metastasis." (PMID 37445902, 2023). "Therefore, perhaps by silencing P2 × 4R, the expression of BDNF/TrkB can be blocked and the proportion of Treg reduced, thus inhibiting the growth of UM tumor cells." (PMID 37563735, 2023). "In addition, expression of PIK3C-delta altered the fibroblast secretome, including PLGF and BDNF, which regulate tumor cell expression of the transcription factor NR4A1, and advanced the aggressiveness of the TNBC population." (PMID 36768435, 2023). "In addition to this, BDNF is thought to produce anti-tumor immune responses during the development and differentiation of neurons." (PMID 36825022, 2023). "This suggests that BDNF may play a role in facilitating the formation of new blood vessels to support tumor growth and metastasis." (PMID 37445902, 2023). "In addition to the BDNF/TrkB axis, the EGFR signaling pathway is associated with tumor cell proliferation, angiogenesis, tumor invasion and metastasis, and apoptosis inhibition." (PMID 37928267, 2023). "It was reported that the BDNF/TrkB axis can promote several important biological processes in several types of cancer, such as cell proliferation, tumor immunosuppression, drug resistance, resistance to anoikis, activation of PI3K/AKT and JAK/STAT3 pathways, EMT, and angiogenesis." (PMID 37679418, 2023). "For example, BDNF is a growth factor that promotes tumor and endothelial cell migration." (PMID 36768435, 2023). "To investigate BDNF in clinical conditions, we assessed whether BDNF levels in CSF (which is in direct contact with tumor tissues) could be used as a potential GBM marker." (PMID 38050515, 2023). "Furthermore, in response to catecholamines, tumor cells produce brain-derived neurotrophic factor (BDNF)." (PMID 37834436, 2023). "BDNF knockdown inhibited not only neurite outgrowth but also stress-induced tumor growth." (PMID 37834436, 2023). "Massive studies have demonstrated that BDNF/TrkB not only can induce nervous system damage via multiple pathophysiological stimuli (such as oxidative stress and inflammation), but also plays crucial roles in tumor pathology." (PMID 37100464, 2023). "Some scholars considered that BDNF may produce oncogenic effects by accelerating tumour growth,proliferation and metastasis through various molecular mechanisms and cell-intrinsic pathways." (PMID 37460933, 2023). "Neuronal CaMKK2 may indirectly influence immunosuppression via supporting tumor growth through the secretion of CaMKK2-dependent mitogenic factors such as BDNF." (PMID 36309495, 2022). "BDNF is known to mediate NSCLC tumor growth via activation of the PI3K/AKT signaling pathway." (PMID 36361620, 2022). "Platelets may therefore be significant regulators of NAS (and BDNF) production in the tumor microenvironment, with consequences for angiogenesis and wider inflammatory-driven processes." (PMID 36613754, 2022). "In particular, it was reported that nerve growth factor (NGF) and brain-derived neurotrophic factor (BDNF) could stimulate tumor cell proliferation, survival, migration, and/or invasion and was beneficial to tumor angiogenesis." (PMID 35833114, 2022). "Furthermore, in line with KDM5C over-expression, CoCl2-treated tumor cells also display BDNF repression and p75NTR upregulation." (PMID 36142158, 2022). "Another explanation to our finding could be that BDNF expression in the tumor is a mere surrogate marker of the pathological glutamate secretion by tumor cells, since glutamate stimulates the production of BDNF by surrounding neurons, glial cells." (PMID 35148403, 2022).
tumor (continued). "Similarly, the intervention decreased circulating tumor-promoting growth factors and inflammatory cytokines (i.e., BDNF, TNFα, FGF-2), with greater effects in obese compared to lean rats." (PMID 35725493, 2022). "Moreover, BDNF is known to mediate its effects on NSCLC tumor growth via activation of the PI3K/AKT signaling pathway." (PMID 36361620, 2022). "Interestingly, cancer cells have been shown to secrete neurotrophic factors (e.g., brain-derived neurotrophic factor) and to guide axons towards the tumor." (PMID 33868585, 2021). "Significant reductions in BDNF were observed postoperatively in patients with small tumours (i.e., below the median size; p = 0.023), in patients with negative angio- or lymphatic invasion (p = 0.028, p = 0.011, respectively), and in patients with lymph node ratios above 0.17 (p = 0.043)." (PMID 34395067, 2021). "Thus, we performed prognostic analysis of BDNF to define BDNF as tumor oncogene or tumor suppressor, and similar results had been achieved by our study." (PMID 34777634, 2021). "Notably, the protective effect of non-antigen-specific IgA disappeared in both RAG1-deficient and NSG mice and tumour-derived TSPAN7 and BDNF antibodies showed decreased anti-tumour effects, consistent with the capacity to transcytose through tumour cells." (PMID 33536615, 2021). "In these patients, the BDNF concentration declined significantly when the primary tumour was resected; thus, it might be considered a potential indicator of complete resection." (PMID 34395067, 2021). "That study showed that BDNF/TrkB expression was preferentially elevated in aggressive tumours, and that it could promote alignancy growth, invasion, and metastasis." (PMID 34395067, 2021). "In addition, neuronal‒GBM cell interactions have recently emerged as an important factor in tumor growth, as neuronal activity promotes tumor progression by inducing the release of brain-derived neurotrophic factor (BDNF), neuroligin-3, and dopamine." (PMID 34439156, 2021). "Interestingly, the binding of BDNF to its receptor, tyrosine kinase receptor B (TrkB), promotes the proliferation, invasion, and metastasis of tumor cells and induces tumor immunosuppression." (PMID 33628340, 2021). "BDNF levels were correlated with tumour volume, and with neuro-, angio- and lymphatic invasions." (PMID 34395067, 2021). "Serum BDNF also correlated with tumor size, tumor differentiation, and TNM staging (p < 0.05)." (PMID 33628340, 2021). "At the same time, it has also been shown that BDNF overexpression in the hypothalamus has immune-augmenting properties, provoking an increased anti-tumor immune response and reducing the activity of proteins that would normally confer resistance to chemotherapy." (PMID 34690699, 2021). "The activation of the receptor TrkB by BDNF also plays an important role in tumor progression." (PMID 34307378, 2021). "Interestingly, they found that BDNF levels were higher in tumours with lymphatic/vascular invasion, compared with tumours without lymphatic/vascular invasion, consistent with results presented previously." (PMID 34395067, 2021). "The tumor suppressor gene, Pdcd4 is an endogenous inhibitor of BDNF translation." (PMID 33960267, 2021). "In summary, BDNF might affect patient prognosis by interacting with tumor-infiltrating Th2 cells, thus serving as a potential prognostic biomarker in PAAD." (PMID 34777634, 2021). "However, there is limiting evidence regarding the BDNF-correlated functions in tumor immunology, and more comprehensive analysis of BDNF profile in PAAD is expected to understand the precise functions of BDNF in prognosis and tumor immune infiltration." (PMID 34777634, 2021). "However, high serum levels of BDNF (p = 0.036) were significantly correlated with tumor differentiation." (PMID 33628340, 2021).